TMEM231 (transmembrane protein 231)
Description:
Transmembrane component of the tectonic-like complex, a complex localized at the transition zone of primary cilia and acting as a barrier that prevents diffusion of transmembrane proteins between the cilia and plasma membranes. Required for ciliogenesis and sonic hedgehog/SHH signaling (By similarity).
Synonyms: FLJ22167; ALYE870; PRO1886; JBTS20; MKS11
Tractability: Antibody: UniProt predicts a signal peptide or a membrane-spanning region; its Gene Ontology location is reachable by antibodies, with medium confidence. PROTAC: ubiquitination databases record sites on it.
Gene: Protein-coding gene on chromosome 16 (75,536,741 to 75,556,289, reverse strand). Ensembl gene ENSG00000205084.
Subcellular location: Cell projection, cilium membrane
Subcellular location (Human Protein Atlas): Vesicles; Golgi apparatus; Mid piece
Gene Ontology:
Molecular function: protein binding
Biological process: cilium assembly; protein localization to ciliary transition zone; regulation of protein localization; smoothened signaling pathway
Cellular component: ciliary membrane; ciliary transition zone; MKS complex; membrane
Genetic constraint (gnomAD): Loss-of-function variants: 25 observed, 24.76 expected, observed/expected ratio (o/e) 1.01, 90% interval 0.74 to 1.41. The synonymous counts are far from expectation, so gnomAD's model fits this gene poorly and the ratio says little. Missense variants: 341 observed, 298.55 expected, observed/expected ratio (o/e) 1.14, 90% interval 1.04 to 1.25. Synonymous variants: 174 observed, 123.73 expected, observed/expected ratio (o/e) 1.41, 90% interval 1.24 to 1.6.
Gene-disease validity (ClinGen):
ClinGen rates the evidence that TMEM231 causes each of these diseases.
ciliopathy (autosomal recessive): Definitive. A genetic disorder of the cellular cilia or the cilia anchoring structures, the basal bodies, or of ciliary function.
Homologues: Orthologues: dog TMEM231 (90% identical), rabbit TMEM231 (89% identical), pig TMEM231 (87% identical), mouse Tmem231 (87% identical), rat Tmem231 (87% identical), guinea pig TMEM231 (86% identical), chimpanzee TMEM231 (85% identical), tropical clawed frog tmem231 (59% identical), macaque TMEM231 (56% identical), zebrafish tmem231 (53% identical), Drosophila melanogaster CG14020 (24% identical), Caenorhabditis elegans tmem-231 (20% identical).
Diseases named in the same sentence as TMEM231 in open-access papers:
TMEM231 is named in the same sentence as 19 diseases in open-access papers, as found by Europe PMC text mining. Sharing a sentence is not in itself a finding about the gene and the disease. The quoted sentences say what the papers report.
ciliopathies (7 papers, 2016 to 2022). "Four different homozygous single nucleotide variants (SNVs) were detected in 4 known ciliopathy genes (TMEM231,TMEM138,WDR19 andBBS9) and were confirmed by Sanger sequencing." (PMID 34354814, 2021). "Accordingly, mice with mutations in Tmem231 display a clear ciliopathy phenotype including renal cystic disease, malformations of the hepatic ductal plate and skeletal abnormalities." (PMID 27141300, 2016). "Recent data identified mutations in TMEM231 in two affected OFDIII siblings during a targeted medical sequencing of 1056 individuals with nephronophthisis-related ciliopathies." (PMID 27141300, 2016). "Pleiotropy is a common characteristic of ciliopathies; mutations in TMEM231 gene with different degrees of severity may cause JBTS, MKS, or oral–facial–digital syndrome (OFDS)." (PMID 34912761, 2021). "Tmem231 mutant mouse embryos also exhibit ciliopathy hallmarks such as polydactyly, microphthalmia, and dorsalization of the neural tube." (PMID 34912761, 2021). "We investigated multiple mouse models of human ciliopathies (including Tctn2, Cc2d2a, and Tmem231 mutants) and discovered that each displays hypotelorism, a narrowing of the midface." (PMID 34672258, 2021). "As WES does not apply to detecting large deletions, ciliopathy patients who were only detected one heterozygous TMEM231 variant should be further examined." (PMID 34912761, 2021).
Joubert syndrome (6 papers, 2019 to 2025). Joubert syndrome (JS) is characterized by congenital malformation of the brainstem and agenesis or hypoplasia of the cerebellar vermis leading to an abnormal respiratory pattern, nystagmus, hypotonia, ataxia, and delay in achieving motor milestones. "Mutations in TMEM231 gene may contribute to the Joubert syndrome (JBTS) or Meckel–Gruber syndrome (MKS)." (PMID 34912761, 2021). "Mutations in TMEM231 gene can contribute to the Joubert syndrome (JBTS, OMIM# 614970) or Meckel–Gruber syndrome (MKS, OMIM# 615397)." (PMID 34912761, 2021). "For example, homozygous variants in TMEM231, ranging from missense to null, are associated with diverse phenotypes, including Meckel–Gruber syndrome (MKS), orofaciodigital syndrome (OFD) type 3, and Joubert syndrome (JBTS)." (PMID 37628633, 2023). "We examined the genes IFT57 (mutated in orofaciodigital syndrome (OFD, OMIM #311200)), BBS2 (Bardet-Biedl syndrome (BBS, OMIM #209900)), (TMEM231 (Meckel-Gruber syndrome (MKS, OMIM #249000)), TCTN2 (Joubert syndrome, (JBTS, OMIM #213300))." (PMID 32445086, 2020).
orofaciodigital syndrome (2 papers, 2020 to 2021). Two syndromes of oral, facial, and digital malformations. "Human CC2D2A mutations cause Meckel and Joubert syndromes, and TMEM231 mutations cause Meckel, Joubert, and Orofaciodigital syndromes." (PMID 34672258, 2021).
autism (1 paper, 2019). Persistent deficits in social interaction and communication and interaction as well as a markedly restricted repertoire of activity and interest as well as repetitive patterns of behavior. "Other members of the TMEM gene family, TMEM132E and TMEM132D genes are associated with bipolar and panic disorders, respectively, while TMEM231 is a known syndromic autism gene." (PMID 31323913, 2019).
Cerebellar dysplasia (1 paper, 2021). Cerebellar dysplasia (abnormal growth or development) is defined by abnormal cerebellar foliation, white matter arborization, and gray-white matter junction.
microcephaly (1 paper, 2021). A congenital or acquired developmental disorder in which the circumference of the head is smaller than normal for the person's age and sex. "TMEM231, initially implicated in JBTS and MKS, also caused unclassified OFDS, with cerebellar hypoplasia, severe microcephaly, or polycystic kidney disease." (PMID 34912761, 2021).
Nystagmus (1 paper, 2022). Rhythmic, involuntary oscillations of one or both eyes related to abnormality in fixation, conjugate gaze, or vestibular mechanisms. "The genetic variants of TCTN3, CC2D2A, TMEM231, and TCTN2 were related to the clinical subgroups with nystagmus or retinopathy." (PMID 35456484, 2022).
cancer (1 paper, 2022). A tumor composed of atypical neoplastic, often pleomorphic cells that invade other tissues. "The duplication encompasses 6 genes four of which are frequently deregulated in cancer (TMEM170A, CHST6, CHST5, TMEM231)." (PMID 35221838, 2022).
TMEM231 also shares sentences with these, for which no sentence is quoted: Meckel syndrome (4 papers); Joubert syndrome 20 (2); Bardet-Biedl syndrome (1); Hydrocephalus (1); panic disorder (1); polycystic kidney disease (1); polydactyly (1); retinal ciliopathy (1); retinal diseases (1); retinopathy (1); Usher syndrome (1).